EPCAM (epithelial cell adhesion molecule)
Diseases named in the same sentence as EPCAM in open-access papers (continued):
Sharing a sentence is not in itself a finding about the gene and the disease.
cancer (continued). "Similarly, the transmembrane glycoprotein EpCAM on cancer stem cells was analyzed by flow cytometry and indicated that the EpCAM(+) subpopulations in MDA-MB-231 mammospheres (Day 14) were not inhibited by olaparib alone but significantly suppressed by Oligo-Fucoidan and the combined treatment." (PMID 36109724, 2022). "Additionally, immunotherapy targeting EpCaM-expressing cancer stem cells (CSCs) with chimeric antigen receptor (CAR) T cells therapy has been attempted recently in a preclinical model of PCa, which suggests immunotherapy against CSCs is a promising therapeutic strategy for PCa." (PMID 36034466, 2022). "In addition, it is also reported that intracellular signaling pathways of cancer cells could be activated by cross-linking of cell surface molecules (such as EpCAM) following antibody binding, perturbing subsequent analyses." (PMID 35311070, 2022). "Therefore, we must carefully validate whether the neoantigen screening from EpCAM+ cancer cells is commonly expressed in heterozygous cancer cells." (PMID 36293034, 2022). "Thus, protein expression of SMAD4P130L was evident in EpCAM+ cancer cells." (PMID 36293034, 2022). "Moreover, the expression of neoantigens of EpCAM+ cancer cells in MPE should be monitored during disease progression, because a decreased CD8+ T cell response to SMAD4P130L might occur due to the loss of the SMAD4P130L antigen in MPE2nd." (PMID 36293034, 2022). "As we discussed in this review, the upregulation of EpCAM and c-Met takes place in many human carcinomas and is in close relation to the development and propagation of cancers; thus, suppressing overexpression of EpCAM and c-Met may represent a potential potent therapeutic approach." (PMID 35986321, 2022). "In addition to EpCAM, numerous other cancer-specific proteins are used for CTC isolation." (PMID 35056131, 2022). "In addition, therapeutic methods targeting EpCAM have shown potential for cancer treatment." (PMID 36369033, 2022). "Thus, we focused on the second possibility, which is to determine whether exosomes derived from cancer cells (or blood cells) induce CD45+EpCAM+ cell formation." (PMID 35711455, 2022). "EpCAM and CD73 bispecific antibodies could selectively targeting EpCAM+ carcinoma-derived EVs." (PMID 36369033, 2022). "While circulating EpCAM-positive cells represent a solid foundation for the capture of CTCs, an antibody-cocktail—preferably one that is generalizable across multiple cancer types—could represent the most ideal solution for increasing sensitivity of these CTC capture platforms." (PMID 34572297, 2021). "EpCAM, a cell surface protein, is over-expressed on a variety of epithelial-derived carcinomas, including adenocarcinomas of colon, stomach, pancreas, lung, ovarian, and breast and plays important roles in modulating cell adhesion and signalling pathways in cancers." (PMID 34802459, 2021). "Such discrepancy suggests that EpCAM may have a different role in each type of cancer." (PMID 34453639, 2021). "To investigate whether cancer-associated EpCAM mutations affect its cellular localization, and/or its potential to inhibit CTSL, we cloned multiple cancer-associated EpCAM mutations in expression vectors alone, or fused to GFP at the C-terminal, and tracked EpCAM localization in vitro." (PMID 33980181, 2021). "EpCAM is silenced in various cancer types, and silencing may exceed the observed rate of mutations." (PMID 33980181, 2021). "These contradictory observations on the role of EpCAM in mediating cell EMT probably suggest that there might be a window or stage that requires different functions of EpCAM during the process of cancer cells undergoing EMT and further participating in the metastasis process." (PMID 33691694, 2021).
cancer (continued). "Levels of both CD24 and EpCAM in EVs were shown to decrease among responding patients (n = 8, 1–6 directed surgical resection, 8 and 9 treated with chemotherapy), indicating that the proposed device could be used to monitor response to cancer therapies." (PMID 34855021, 2021). "Furthermore, the infiltration of XBP1+ TAMs, especially XBP1+ CD206+ (representing the XBP1 activation in TAMs), in tumors was associated with shorter DFS in CRC patients, but not XBP1+EPCAM+ (representing the XBP1 activation in cancer cells)." (PMID 34667145, 2021). "CAFs are primarily defined as cells that lack lineage markers for epithelial cells (Epithelial Cell Adhesion Molecule or EpCAM or CD326), endothelial cells (CD31), and leukocytes (CD45); possess elongated, spindle-shaped morphology; and lack the mutations found within the cancer cells." (PMID 34948209, 2021). "We describe an association of EpCAM with numerous proteins involved in vesicle and membrane trafficking and demonstrate endocytosis and membrane recycling of EpCAM under physiological conditions during differentiation of ESC and upon EMT induction in carcinoma cells." (PMID 34693227, 2021). "Furthermore, using the MACS enrichment with prior permeabilization to EpCAM staining does not rule out the possibly of detecting cancer associated macrophage-like (CAMLs) cells." (PMID 32197486, 2020). "Upon EpCAM regulated intermembrane proteolysis, the solubilized extracellular domain could act as a ligand for receptor tyrosine kinases (RTKs) and activate the several oncogenic signalling pathways that would in turn support cancer cells growth and fitness." (PMID 32046162, 2020). "In different solid cancers, we and other groups have identified a distinct circulating cancer-associated cell that is large, polymorphic in shape, often polynuclear (≥1 DAPI+ nucleus), with a dual epithelial and macrophage/myeloid phenotype (dual CK+/EpCAM+ and CD14/CD45+)." (PMID 32182935, 2020). "Surprisingly, there are not many known mutations in the EPCAM gene linked to cancer." (PMID 32486423, 2020). "Moreover, the prognostic value of EpCAM expression might be different depending on the type of cancer." (PMID 32764280, 2020). "Dual selection with anti-FAPα and -EpCAM antibodies provides high positivity and specificity, and might be used to monitor and to obtain precious information on resistance to combination therapies and on cancer progression." (PMID 32260071, 2020). "Based on our in vitro findings in GCT and early clinical experience of EpCAM-redirected immunotherapy in other epithelial EpCAM-positive cancer entities, such therapeutics may also prove beneficial for the treatment of cisplatin-resistant GCT and warrant clinical exploration." (PMID 32438548, 2020). "However, single immunomagnetic anti-EpCAM-based detection assays have major limitations and may underestimate the real number of CTCs in cancer patients." (PMID 32197486, 2020). "To determine whether targeted liposomes DARP-Lip(Bn) and fusion toxin EC1-LoPE possess synergistic cytotoxic effect on HER2/EpCAM-positive cancer cells, we incubated BT-474 and MDA-MB-231 cells with different concentrations of DARP-Lip(Bn) and EC1-LoPE and assessed cytotoxicity after 72 h by MTT." (PMID 33081407, 2020). "Therefore, specific targeting or ablation of these EpCAM expressing cancer stem cells could be developed as novel cancer therapeutic strategies." (PMID 32046162, 2020). "Both transgenic plants carrying EpCAM fused to IgM Fc, and J-chain recombinant protein transgenes were crossed to generate F1 transgenic plants and investigate the potential of Chinese cabbage as a plant bioreactor to produce highly valuable antigen–Fc complex proteins for cancer immunotherapy." (PMID 33143243, 2020).
cancer (continued). "For example, prospective studies on the expression of EGFR and EpCAM might shed light on the power of EpCAM expression to predict treatment response in carcinoma entities that implement a therapy with the anti-EGFR monoclonal antibody cetuximab or small molecule inhibitors of EGFR." (PMID 32507912, 2020). "Thus, EpAb2-6 is an anti-EpCAM antibody that inhibits central EpCAM signaling functions, which might represent a novel approach to treatment methods targeting EpCAM in carcinomas." (PMID 32507912, 2020). "However, there is also in vitro evidence that claudin-7 cooperates with epithelial cell adhesion molecule (EpCAM) and generates EpIC, a co-transcription factor that collaborates with β-catenin in cancer initiating cells, contributing to EMT and cancer metastasis." (PMID 31316506, 2019). "Thus, liquid biopsy analyses open new avenues to study the relevance of EpCAM for cancer metastasis and may lead to improvements in the personalized management of cancer patients." (PMID 31225512, 2019). "Although this relationship does not have a well-defined mechanism, one hypothesis is that HBV promotes hepatocarcinogenesis through the development of cancer stem cells through the activation of Wnt/β-catenin signaling pathways, thus leading to an overexpression of EpCAM." (PMID 30112355, 2018). "What makes EpCAM a very interesting molecule for targeted therapeutics though, is that it is localised to the basolateral membrane in normal epithelial tissue, but during the progression from normal cell to cancer cell, the expression pattern changes to an intense uniform membranous over-expression." (PMID 29329202, 2018). "Hence, we disclose a regulatory signaling cross talk between EGFR and EpCAM in cancer cells that impacts proliferation and EMT and may thus have substantial repercussions on disease progression and outcome." (PMID 30261040, 2018). "The hypothesis that cancer-specific antibody can be fused with anti-CD3 antibody to redirect T cell mediated killing effect in cancer patients have been supported by the approval of catumaxomab (anti-EpCAM and anti-CD3,) and blinatumomab (anti-CD19 and anti-CD3,)." (PMID 29857542, 2018). "Moreover, cell membrane protein (nucleolin, mucin and epithelial cell adhesion molecule)-specific, aptamer-conjugated isotopic GIANs were fabricated and feasibly applied to built-in coding for rapid imaging and pattern recognition of targeted cancer cells." (PMID 29732070, 2018). "EVs carry molecules such as CD24, and epithelial cell adhesion molecule (EPCAM1), which directly regulate cancer-cell migration, proteases (MMP2, MMP9), which promote ECM degradation and cancer invasiveness, or EV-associated mRNAs, such as miR21, which may induce resistance to paclitaxel." (PMID 30200478, 2018). "Molecular functions of EpCAM that could be the cause of this restrictive expression have primarily been studied in cancer cells and might thus not be entirely transferred to non-pathologic differentiation processes." (PMID 29379062, 2018). "Thus, this chip is useful for the capture of mesenchymal-like cells, even though a range of cancer type which anti-EGFR antibody can capture may be narrower than that anti-EpCAM antibody captures." (PMID 30104638, 2018). "In addition, we demonstrated that BCYRN1 might regulate the expression of EpCAM, which is closely related to carcinogenesis and progression of cancers." (PMID 29435146, 2018). "Moreover, the cancer stem cell markers EPCAM and NANOG were up-regulated by HOXB7." (PMID 28646927, 2017). "In addition, EpCAM could be considered an interesting target for immunotherapy, since it is highly expressed on the cell surface of multiple human carcinomas." (PMID 28531111, 2017). "The heterogenous expression of EpCAM in cancer cells may be related to the EMT process." (PMID 27013581, 2016).
cancer (continued). "To test whether our EpCAM aptamers are able to bind to EpCAM on the surface of human cancer cells from different pathological originals according to the previous report, we studied the interaction of EpCAM ALB aptamers with EpCAM-positive cell lines using flow cytometry and confocal analysis." (PMID 27886058, 2016). "Based on the well founded hypothesis that cell specific MPs (200–1000 nm in size) are released into the circulation as a result of activation and/or apoptosis of their parent cell type, we searched for EpCAM+, CD147+ or EpCAM+CD147+ double positive taMPs that could indicate cancer presence." (PMID 27127176, 2016). "Moreover, EPCAM-targeted antibodies and EPCAM-targeted drug delivery have been developed and tested for the treatment of carcinomas in vitro and in vivo, although evidence for the clinical efficacy and safety of EPCAM-targeted therapy in human cancer patients remains insufficient." (PMID 26528695, 2016). "However, it has been suggested that the methods based on the expression of EpCAM underestimate the number of CTCs and may miss a metastatic subpopulation of CTCs with cancer stem cell (CSC) properties." (PMID 26317979, 2015). "Therefore, the platelet-cloaked cancer cell aggregates should be EpCAM+CD61+." (PMID 26459390, 2015). "The decreased cell activity might be mainly attributed to the presence of EpCAM on cancer cells." (PMID 25643843, 2015). "Previous studies demonstrated that high affinity anti-EpCAM antibodies could cause toxic effects (phase I trials), while antibodies with moderate affinity to EpCAM-positive cancers efficiently mediated both antibody-dependent cellular cytotoxicity and complement-mediated cytotoxicity." (PMID 25960617, 2015). "Therefore, the adoptive transfer of T cells targeting EpCAM could have great potential as a cancer treatment." (PMID 25636521, 2015). "However, it has been recognized that clinical application of such strategy could be significantly limited due to highly heterogeneous and dynamic expression of EpCAM among different cancer cells." (PMID 25909226, 2015). "We chose these biomarkers for CTC characterization, because EpCAM and CK are commonly used for epithelial CTC detection, and previous studies have demonstrated that the expression of the mesenchymal markers twist or vimentin in CTCs is associated with cancer metastasis." (PMID 25909322, 2015). "However, much of the research on the role of EpCAM in the liver has focused on carcinomas." (PMID 25477371, 2015). "The versatility of CTC enumeration by OBP-401 may overcome the drawback of an immunocapturing method such as EpCAM since it is known that epithelial features of cancer cells are lost and changed to mesenchymal ones during metastasis or invasion (i.e., epithelial-mesenchymal transition)." (PMID 25176113, 2014). "Notably, several drugs have been developed to target EPCAM as cancer therapeutics." (PMID 24944582, 2014). "EpCAM is a bona fide cancer cell marker although downregulation may occur during EMT." (PMID 25291178, 2014). "Interestingly, even within one cancer entity, correlation of EpCAM expression with overall survival may vary across intrinsic subtypes." (PMID 24009667, 2013). "However, accumulating evidence suggests that the expression of EpCAM during cancer progression and in particular during epithelial-to-mesenchymal transition has not been well characterized, raising concerns about the universality of this antigen for immunocapture systems." (PMID 22558290, 2012). "Thus, it is clear that EpCAM+ Y79 cells behave like cancer stem cells." (PMID 22328825, 2012). "Moreover, EpCAM has emerged as a promising target structure on cancer stem cells." (PMID 23110550, 2012). "However, the functional role of EpCAM in cancer invasion remains controversial." (PMID 22132731, 2011). "Finally, EpCAM represents an attractive target for molecular therapy in epithelial carcinomas." (PMID 22132731, 2011).
cancer (continued). "In addition, EpCAM physically interacts with the metastasis-promoting cell surface receptor CD44v4-V7 and the tight junction component Claudin7, possibly blocking Claudin function during invasion and metastasis of several carcinomas." (PMID 19609345, 2009). "We demonstrate the flexibilityof this platform by equipping SpyTag-AAVswith DARPins targeting EGFR, EpCAM, and HER2, which successfully redirectedthe vector to the corresponding cancer cell lines." (PMID 41430475, 2026). "We demonstrated this modularity by equipping the vector withdifferent SpyCatcher-DARPin fusion proteins specific for EGFR, EpCAM,and HER2/ErbB2, thereby achieving efficient and specific transductionof corresponding cancer cell lines." (PMID 41430475, 2026). "This was expected, as the CellMagTM system is based on the CellSearch®, which is the gold standard for EpCAM‐positive CTC isolation and FDA‐approved for certain cancers." (PMID 39105395, 2025). "By avoiding EpCAM-based positive selection, the RosetteSep system ensures a more comprehensive representation of CTC heterogeneity, which is crucial for accurate cancer diagnosis and monitoring." (PMID 40076201, 2025). "The use of ELISA-based methods for the quantification of proteins specific to cancer-derived exosomes, such as CD44, CD44v6, CD9, EpCAM, and CD81, has been well-documented." (PMID 41573685, 2025). "Solotimab, a bsAb targeting EpCAM and CD3, showed effective T cell activation and cancer cell lysis in vitro." (PMID 40707958, 2025). "These genes were also connected with other genes notably deregulated in cancer as ANGPTL1, ADAMTSL2, PELI2 and EPCAM." (PMID 41231825, 2025). "In cancer tissues, 93% (+/−SEM 1.3%) of the EpCAM-/FAP+ fibroblasts were also IL1R+ and 96% (+/−SEM 0.8%) were also Ly6C+, suggesting a high feature of plasticity between myCAF and iCAF populations." (PMID 40523922, 2025). "In the spectrum of 33 human cancer types, CLDN3 demonstrates an expression pattern that closely mirrors EpCAM’s." (PMID 40057807, 2025). "While proteins, such as EpCAM and CD24, were among the first biomarkers studied in EVs derived from malignant ascites, more recent works have explored the EVs biocargo, focusing particularly on miRNAs." (PMID 40259212, 2025). "Organoid targeting was studied with NK-92 cells expressing CAR for the epithelial cell adhesion molecule (EPCAM), the neoantigen EGFRvIII found in several cancers, or the Frizzled receptor upregulated in some CRC patients." (PMID 40136707, 2025). "Most of them measured either cancer-related proteins (i.e., PSMA, PCA3, TMPRSS2:EGR, or PSA) or exosomal cell surface proteins (CD9, CD3, EpCAM, or CD81)." (PMID 39859516, 2025). "Both treatment doses elevated the Bax/Bcl-2 ratio and reduced the expression of cancer stem cell markers CD44, EpCam, and VEGF compared to controls." (PMID 40371330, 2025). "It is likely that CTCs from the cancer patients included in this study had undergone substantial EMT, reducing the number of cells detected with the anti-EpCAM antibody." (PMID 40718490, 2025). "Three Raman tags with distinctive Raman spectra were used to report three different protein markers on individual cancer cells, with QSY21 for CD44, BHQ3 for EpCAM, and QXL680 for HER2." (PMID 39997827, 2025). "CD44, CD133, Epithelial cell adhesion molecule (EpCAM/CD326), stage-specific embryonic antigen-4 (SSEA-4), CD146 are expressed on the surface of EVs originating from cancer stem cells and bind their specific antibodies immobilized on the beads." (PMID 40106404, 2025). "The topmost expressed epitopes in ascitic fluid EVs were CD326/EpCAM, CD133/1, HLA-DR, CD24 and CD44, which are cancer-related markers." (PMID 40259212, 2025). "This strategy enabled the detection of surface proteins (e.g., CD63, EpCAM, PSMA, and Nucleolin) on exosomes from various cancer cell lines, including HepG2, MCF-7, HeLa, HEK-293T, and L-02 cells." (PMID 39943486, 2025).